GLOD4 (glyoxalase domain containing 4)
Synonyms: C17orf25; CGI-150; HC71; HC6
Tractability: PROTAC: ubiquitination databases record sites on it; its protein half-life has been measured.
Gene: Protein-coding gene on chromosome 17 (757,097 to 782,341, reverse strand). Ensembl gene ENSG00000167699.
Subcellular location: Mitochondrion
Subcellular location (Human Protein Atlas): Cytosol
Gene Ontology:
Molecular function: cadherin binding
Cellular component: extracellular exosome; mitochondrion
Genetic constraint (gnomAD): Loss-of-function variants: 8 observed, 6.87 expected, observed/expected ratio (o/e) 1.16, 90% interval 0.67 to 1.84. That is too few expected variants to judge how well the gene tolerates losing a copy. Missense variants: 115 observed, 102.24 expected, observed/expected ratio (o/e) 1.12, 90% interval 0.97 to 1.31. Synonymous variants: 47 observed, 40.01 expected, observed/expected ratio (o/e) 1.17, 90% interval 0.93 to 1.5.
Homologues: Orthologues: macaque GLOD4 (98% identical), chimpanzee GLOD4 (93% identical), dog GLOD4 (92% identical), mouse Glod4 (92% identical), zebrafish glod4 (74% identical), tropical clawed frog glod4 (69% identical), Drosophila melanogaster CG1532 (49% identical), Caenorhabditis elegans glod-4 (46% identical). Paralogues in human: GLO1 (16% identical).
Diseases named in the same sentence as GLOD4 in open-access papers:
GLOD4 is named in the same sentence as 13 diseases in open-access papers, as found by Europe PMC text mining. Sharing a sentence is not in itself a finding about the gene and the disease. The quoted sentences say what the papers report.
hepatocellular carcinoma (3 papers, 2019 to 2024). A malignant tumor that arises from hepatocytes. "The GLOD4 gene (C17orf25) is found in a region on human chromosome 17 showing high heterozygosity in human hepatocellular carcinoma." (PMID 39302370, 2024). "Glyoxalase domain-containing protein 4 (GLOD4), a glyoxalase-domain containing protein also known as HC71, CGI-150 or C17orf25, belongs to the glyoxalase I family, which was firstly isolated from hepatocellular carcinoma in humans." (PMID 31614839, 2019). "GLOD4, also known as HC6-type or HC71-type, was originally cloned as the C17orf25 cDNA from human hepatocellular carcinoma." (PMID 39272396, 2024).
Alzheimer disease (1 paper, 2024). A progressive, neurodegenerative disease characterized by loss of function and death of nerve cells in several areas of the brain leading to loss of cognitive function such as memory and language. "Glyoxalase domain containing protein 4 (GLOD4), a protein of an unknown function, is associated with Alzheimer’s disease (AD)." (PMID 39302370, 2024).
ciliopathy (1 paper, 2013). A genetic disorder of the cellular cilia or the cilia anchoring structures, the basal bodies, or of ciliary function. "We chose to look at GLOD4 because it had no previous support for a role in cilia, although it was shown to be differentially up-regulated in a canine model of retinal degeneration, a common ciliopathy phenotype." (PMID 23604077, 2013).
neuroblastoma (1 paper, 2024). Neuroblastoma (NB) is the most common solid, extracranial childhood tumor. "We also examined Glod4 expression in Blmh–/–5xFAD mouse model of AD in relation to cognitive/neuromotor performance in these mice and biochemical consequences of Glod4 gene silencing in mouse neuroblastoma N2a-APPswe cells." (PMID 39302370, 2024). "Glod4 gene in mouse neuroblastoma N2a-APPswe cells was silenced by RNA interference and Glod4, Aβ precursor protein (Aβpp), Atg5, p62, and Lc3 proteins and mRNAs were quantified." (PMID 39302370, 2024). "To elucidate the mechanism by which Glod4 can affect behavioral hallmarks of AD, we first examined whether our findings of downregulated GLOD4 expression in brains of AD patients can be recapitulated in mouse neuroblastoma cells N2a-APPswe carrying a mutated human AβPP transgene." (PMID 39302370, 2024).
prostatitis (1 paper, 2025). An infectious or non-infectious inflammatory process affecting the prostate gland. "We revealed two Tier 2 genes (NOA1 and ELAC2) and one Tier 3 gene (ACAT1) for BPH, two Tier 3 genes (TRMU and SFXN5) for prostatitis, and six Tier 3 genes (MRPL24, NDUFS6, PUS1, NBR1, GLOD4, and PCBD2) for PCa." (PMID 40919435, 2025). "Our analysis revealed two Tier 2 genes (NOA1 and ELAC2) for BPH, two Tier 3 genes (TRMU and SFXN5) for prostatitis, and six Tier 3 genes (MRPL24, NDUFS6, PUS1, NBR1, GLOD4, and PCBD2) for PCa." (PMID 40919435, 2025).
cancer (1 paper, 2011). A tumor composed of atypical neoplastic, often pleomorphic cells that invade other tissues. "Further studies in larger series of patients are warranted to elucidate this question and determine the specific role of those cancer associated genes (INPP5A, CDX1, MB, CAMK2A, APOL6 vs. VPS53, FAM57A, GEMIN4, SFRS13, ELP2P, GLOD4, CSF2RA and IL3RA), differentially altered in both groups of tumors." (PMID 21811587, 2011).
neurodegenerative disease (1 paper, 2023). A disorder of the central nervous system characterized by gradual and progressive loss of neural tissue and neurologic function. "Recent research identified neurodegenerative diseases to be influenced by metabolism and glod-4 mutants demonstrate increased neuronal damage, decreased lifespan, and increased feeding." (PMID 37728328, 2023).
GLOD4 also shares sentences with these, for which no sentence is quoted: diabetes (1 paper); Hyperglycemia (1); ischemia (1); Obesity (1); retinal degeneration (1); Stroke (1).